MDM2 (MDM2 proto-oncogene)
Diseases named in the same sentence as MDM2 in open-access papers (continued):
Sharing a sentence is not in itself a finding about the gene and the disease.
glioblastoma (124 papers, 1996 to 2026). The most malignant astrocytic tumor (WHO grade IV). "This study describes a novel, pathogenic MDM2(exon 1)::PDGFRA(exon 8) fusion detected after cetuximab treatment in an EGFR-amplified glioblastoma." (PMID 40819143, 2025). "Especially, MDM2 in our identified dysregulated pathway is reported to be associated with glioblastoma in more than 100 previous studies." (PMID 29337288, 2018). "Our finding that the CDK4/MDM2 co-amplicon was associated with CCND2 gain was also seen in glioblastoma multiforme." (PMID 28643781, 2017). "As a result, inactivating mutations in MDM2 may facilitate glioblastoma progression." (PMID 40697329, 2025). "The present results suggest that MDM2 is an Achilles’ heel of glioma stem cells and, thus, has potential as an excellent therapeutic target for patients with glioblastoma." (PMID 38612758, 2024). "From a clinical point of view, the differential sensitivity of glioma stem cells and non-stem glioma cells revealed in this study has profound implications for how MDM2 inhibitors should be used in the treatment of glioblastoma." (PMID 38612758, 2024).
glioblastoma (continued). "For example, ADAMTS9-AS2 was increased in TMZ-resistant glioblastoma cells to enhance chemoresistance by upregulating the FUS/MDM2 axis." (PMID 36816363, 2023). "Among these investigations, MDM2 was primarily changed in glioblastoma, with the highest incidence of modification at 11.90%." (PMID 37049742, 2023). "Similar patterns of high MDM2/CDK4 amplification with large derivative chromosomes were observed in human glioblastoma, and were assigned to chromothripsis, with aggregation of double minute chromosomes." (PMID 35053440, 2022). "While MDM4 alterations were absent in FGFR3-TACC3 fusion-positive gliomas, there is an association with a higher prevalence of MDM2 alterations and CDK4 amplifications, which can be found in 19% and 10%, respectively, of fusion-positive glioblastoma." (PMID 35955806, 2022). "Another KDM4C target gene, MDM2, exhibited a similar expression correlation pattern in glioblastoma samples." (PMID 33462212, 2021). "Both CDK4 and MDM2 are known to be hyper-amplified in glioblastoma, often by double minute chromosomes." (PMID 34891161, 2021). "The Erbb3, Gli1 and Mdm2 genes are all present in this region, and their amplification is known to have effects in human glioblastoma." (PMID 33435218, 2021). "Epidermal growth factor receptor (EGFR) overexpression, PTEN (MMAC I) mutation, CDKN2A (p16) deletion, and less frequently MDM2 amplification are just a few defects which lead to uncontrolled proliferation, invasion, and angiogenesis in primary glioblastoma (GBM)." (PMID 32178454, 2020). "Our observations are consistent with a previous report that MDM2 inhibition by nutlin3a enhanced the efficacy of TMZ in glioblastomas." (PMID 32630235, 2020). "Our data provide new evidence that glioblastoma stem cells have high susceptibility to AMG232 suggesting the potential clinical implications of MDM2 inhibition for glioblastoma treatment." (PMID 30022047, 2018). "The screen statistics and additional verification of the assay established sufficient confidence to utilize the assay in prediction and selection of glioblastoma patients who are likely to respond to the MDM2 inhibitors in the future." (PMID 30022047, 2018). "MET and MDM2 amplifications were seen in 3 out of 78 (3.8%) and 17 out of 110 cases (15.5%) molecular glioblastomas respectively tested for these amplifications." (PMID 30470264, 2018).
glioblastoma (continued). "Here, we compared the effects of these two clinical MDM2 inhibitors in six glioblastoma cell lines and ten patient-derived glioblastoma stem cells." (PMID 30022047, 2018). "CDK4 and MDM2 were amplified during differentiation of neural progenitor cells, in neural stem cells, and in glioblastoma." (PMID 29416732, 2018). "Their preclinical study has shed light on potential clinical implication of using MDM2 inhibition strategies to fight glioblastoma." (PMID 30022047, 2018). "These suggest that targeting MDM2 should be considered as one of treatment options for glioblastoma." (PMID 30022047, 2018). "These will facilitate additional preclinical and clinical studies evaluating MDM2 inhibitors in glioblastoma and direct further efforts towards developing better MDM2-targeted therapeutics." (PMID 30022047, 2018). "Collectively, this study provides an important new insight into the effects of MDM2 inhibition and suppression of glioblastoma stemness using AMG232." (PMID 30022047, 2018). "FOXO1 and AKT1, along with MDM2 (another common intermediary gene in the PIN) have previously been identified in differential co-expression studies of glioblastoma." (PMID 28957313, 2017). "Previous studies have shown that the MDM2 gene is amplified and overexpressed in 8–10% of glioblastomas and anaplastic astrocytomas." (PMID 26328271, 2015). "Some of these alterations, such as del (1p36), del (2p21), +7, del (6q27q29)/−6, EGFR (7p11.2), MDM2 (12q15) and CDK4 (12q14.3) amplification, −10, amplification of 15q24.1, del (17p13)/−17, −19, −22 were known to be associated with glioblastomas." (PMID 23472076, 2013). "In another study, among the 5 glioblastomas that contained amplification of either CDK4 or MDM2, only one tumor had both amplified." (PMID 22691727, 2012). "MDM2 is an oncogene which is highly expressed in glioblastoma and it widely participates in tumorigenesis and progression." (PMID 23391506, 2012). "The results provide a basis for the rational use of MDM2 antagonists as a novel treatment option for glioblastoma patients." (PMID 21483692, 2011). "Primary glioblastomas exhibit frequent EGFR amplification, homozygous deletion of CDKN2A and p14ARF, CDK4 amplification, MDM2 or MDM4 amplification, RB1 mutation/homozygous deletion, monosomy 10 and PTEN mutation." (PMID 19333441, 2009). "Amplification of EGFR or MDM2, PTEN mutation as well as homozygous CDKN2A or p14ARF deletions are all rare in secondary glioblastomas." (PMID 19333441, 2009). "We also found no clear correlation between the SNP309 (rs2279744) locus in MDM2 and age of presentation or survival in glioblastoma patients." (PMID 18781178, 2008).
glioblastoma (continued). "Several clinical trials are underway to evaluate MDM2 inhibitors in patients with glioblastoma." (PMID 38612758, 2024). "Our results, which suggest that non-stem, bulk tumor cells are less sensitive to MDM2 inhibitors, may help guide the selection of glioblastoma patients suitable for MDM2 inhibitor therapy." (PMID 38612758, 2024). "In addition to demonstrating the efficient synergistic action of the two compounds, these in vitro data confirmed the blockade of the CXCR4/MDM2/4 axis as a valid strategy to reduce glioblastoma proliferation." (PMID 36980182, 2023). "Here, we used RG7112 and AMG232 to test the effect of MDM2 inhibitors in glioblastoma cells." (PMID 30022047, 2018). "Thus, it was concluded that MEK/ERK/MDM-2 inhibition promotes the commitment of stem-like glioblastoma cells to differentiation and, thereby, minimizes their malignant potential." (PMID 30254823, 2018). "The Mdm2 gene was found amplified or over-expressed in about 10 per cent of glioblastomas." (PMID 26656605, 2015).
glioblastoma (continued). "Taken together, the results of the present study suggest that MDM2 antagonists may provide a novel treatment option for glioblastoma patients." (PMID 21483692, 2011). "In this study, we identify and functionally characterize a novel amplified fusion, MDM2 (exon 1)::PDGFRA (exon 8), mediating resistance to cetuximab in an EGFR-amplified glioblastoma." (PMID 40819143, 2025). "Upon comparing the glioblastoma (GBM) high- and low-expression groups for MDM2, the high-expression group was found to be approximately 50-fold more sensitive to RSL3-induced ferroptosis in cancer cells than the MDM2 low-expression group." (PMID 40959280, 2025). "Of the 34 overexpressed tyrosine kinase genes, MDM2 and CDK4 in glioblastoma, 22 copy number amplifications (64.7%) were observed." (PMID 38363490, 2024). "In orthotopic glioblastoma (GBM) patient-derived brain tumor stem cell (BTSC) xenograft models, treatment with the MDM2 small molecule inhibitor brigimadlin (BI-907828) showed higher survival rates compared to the control group." (PMID 39223632, 2024). "No tumors demonstrated EGFR amplification, MET amplification, CDK4 amplification, MDM2 or MDM4 amplification, PTEN homozygous deletion, or NF1 homozygous deletion that are frequent oncogenic events in conventional IDH-wildtype glioblastomas." (PMID 38079020, 2023). "The combination of RS3594, a dual MDM2/4 inhibitor, and AMD3100 has been successful in reducing the invasiveness and migration of glioblastoma cells." (PMID 36980182, 2023). "Genes known to be the most frequently amplified in glioblastoma, EGFR, CDK4, PDGFRA, MDM2, MDM4 are all found to be involved in tumorigenesis of a variety of cancers and are members of several signaling pathways notoriously involved in cancer." (PMID 30871102, 2019). "In the present study, we tested one of the most potent MDM2 inhibitors, AMG232 in glioblastoma cell lines and patient-derived glioblastoma stem cells for the first time." (PMID 30022047, 2018).